NFKBIA (NFKB inhibitor alpha)
Diseases named in the same sentence as NFKBIA in open-access papers (continued):
Sharing a sentence is not in itself a finding about the gene and the disease.
glioblastoma (continued). "It is important to note that the nonclassical glioblastomas (mesenchymal, proneural, and neural subtypes) frequently display NFKBIA (NF-kB Inhibitor-α, a modulator of NF-kB and EGFR signaling) gene deletions." (PMID 30279357, 2018). "The NFKBIA protein levels detected by western blot analysis (using 50 ng of protein sample) were significantly lower in the glioblastomas harboring the CC and CT genotypes than in the non-cancerous brain tissue samples." (PMID 25215581, 2014). "We analyzed the DNA sequence of the NFKBIA gene from brain tissue samples obtained from 24 glioblastomas patients and 8 non-cancerous subjects." (PMID 25215581, 2014). "We detected the copy number of NFKBIA in 24 cases of glioblastoma samples and in 8 cases of non-cancerous brain tissue samples." (PMID 25215581, 2014). "There was no protein expression of NFKBIA in the non-cancerous brain tissue and glioblastoma samples, and only 1 case of pilocytic astrocytoma showed staining for NFKBIA in a total of 94 gliomas (from tissue microarray analysis in our laboratory)." (PMID 25215581, 2014). "The NFKBIA mRNA levels were lower in the glioblastoma compared with the non-cancerous brain tissue samples." (PMID 25215581, 2014). "In order to examine whether there were significant differences in the expression of NFKBIA protein in glioblastomas compared with non-cancerous brain tissues, we decreased the amount of protein sample." (PMID 25215581, 2014). "We performed qPCR to examine whether there were significant differences in the mRNA expression of NFKBIA in glioblastomas compared with non-cancerous brain tissue samples and in glioblastomas harboring different genotypes of SNP rs1957106." (PMID 25215581, 2014). "Deletion of NFKBIA (encoding nuclear factor of κ-light polypeptide gene enhancer in B-cells inhibitor-α), an inhibitor of the EGFR-signaling pathway, promotes tumorigenesis in glioblastomas that do not have alterations of EGFR and is associated with a poor prognosis." (PMID 22553975, 2012).
viral infection (44 papers, 2005 to 2026). "In addition to the ubiquitin-proteasome regulation of its stability mentioned earlier, translational control of NFKBIA mRNA that encodes for IkBα has been reported as a rapid mechanism for cells to combat viral infections by activating the production of type-I interferon through NF-kB signaling." (PMID 39941899, 2025). "Most patients with NFKBIA mutations manifested anhidrotic ectodermal dysplasia (EDA) features and had high susceptibility to fungal, pyogenic, mycobacterial, and viral infections, as early as three months old, due to immunodeficiency." (PMID 36292785, 2022). "MMP-12 is transported to the nucleus, where it binds to the NF-kappa-B inhibitor alpha NFKBIA promoter and mediates NFKBIA transcription, leading to Interferonα secretion and protection against viral infections." (PMID 33498927, 2021). "A network-based analytical study on comparison between SARS-CoV and MERS-CoV infections strongly advocated a logarithmic scale upregulation in the gene expression of NFKBIA, which has been proposed to be a key regulator in the level of host immune response during virus infection." (PMID 33262955, 2020). "Since NFKBIA is highly expressed in COVID-19 patients and tripartite motif-containing (TRIM) 22 can activate NF-kappaB to protect the host from viral infection, these two genes have a huge impact on immune disparities between the two PYRclusters." (PMID 35928821, 2022). "Additionally, our results revealed that miR-221-5p activated the NF-κB pathway by targeting NFKBIA and SOCS1, inhibitors of NF-κB signaling and mediators of IFN and ISG production, to inhibit viral infection." (PMID 30380612, 2018). "Coherently, we found that viral infection induces the accumulation of an active form of CTNNB1 and that CTNNB1 gene silencing increases SeV-induced IFNB1, IFIT1 and TNF expression, as well as NFKBIA (IκBα) phosphorylation at serine 32 (P-Ser32) to release NF-κB inhibition." (PMID 23785285, 2013).
lung carcinoma (38 papers, 2005 to 2026). "The association between NFKBIA -881A>G polymorphism and the risk of lung cancer according to sex and smoking status is shown in Table-VII." (PMID 26870106, 2015). "Association between combinations of NFKB1 -94 ins/del ATTG polymorphism and NFKBIA -881A>G polymorphism and lung cancer risk is shown in Table-III." (PMID 26870106, 2015). "Association between combinations of NFKB1 -94 ins/del ATTG polymorphism and NFKBIA -881A>G polymorphism and lung cancer risk." (PMID 26870106, 2015). "Association between combinations of NFKB1 -94 ins/del ATTG polymorphism and NFKBIA -826C>T polymorphism and lung cancer risk." (PMID 26870106, 2015). "Association between combinations of NFKBIA -826C>T polymorphism and NFKBIA -881A>G polymorphism and lung cancer risk." (PMID 26870106, 2015). "On the other hand, the heterozygous and homozygous variant genotypes of the NFKBIA polymorphisms appeared to be significantly associated with increased lung cancer risk(P=0.046 for -826CT, P=0.013 for -826TT, P=0.031 for -881AG, P=0.008 for -881GG,)." (PMID 26870106, 2015). "The association between NFKBIA -826C>T polymorphism and lung cancer risk according to sex and smoking status is shown in Table-VI.." (PMID 26870106, 2015). "The association of combinations of NFKB1 -94 ins/del ATTG polymorphism and NFKBIA -826C>T polymorphism with lung cancer risk is shown in Table-II." (PMID 26870106, 2015). "Association between NFKB1 -94 ins/del ATTG polymorphism, NFKBIA -826C>Tpolymorphism and NFKBIA -881A>G polymorphism and lung cancer risk." (PMID 26870106, 2015). "The combinations of NFKBIA -826C>T polymorphism and NFKBIA -881A>G polymorphism and their association with lung cancer risk is shown in Table-IV." (PMID 26870106, 2015). "A significant correlation was observed between the presence of K-ras mutations and high AEG-1 expression (P = 0.04) and high NFKBIA expression (P = 0.04); in the lung cancer cell lines, a similar correlation was found." (PMID 21951562, 2011). "The association between NFKB1 and NFKBIA polymorphisms and lung cancer risk is shown in Table-I." (PMID 26870106, 2015). "To test our hypothesis, we conducted a case-control study to investigate the association of NFKB1 -94 ins/del ATTG polymorphism and NFKBIA -826C>T and -881A>G polymorphisms with the risk of lung cancer in a Chinese population." (PMID 26870106, 2015). "We have showed that the variant alleles of NFKB1 -94 ins/del ATTG polymorphism, NFKBIA -826C>T polymorphism and NFKBIA -881A>G polymorphism could influence the risk of lung cancer in China." (PMID 26870106, 2015). "Here, we unravel a novel NFKBIA amplification in lung cancer and demonstrate a strong link between IκBα overexpression, low-ROS levels and chemoresistance." (PMID 33863364, 2021). "In lung cancer patients, loss of heterozygosity (LOH) in 14q, where the NFKBIA gene is localized, was previously identified." (PMID 34572464, 2021). "Here, by using an in silico approach, following the identification of NFKBIA (the gene encoding IκBα) amplification in various cancers, we described an inverse correlation between IκBα, oxidative metabolism, and ROS production in lung cancer." (PMID 33863364, 2021). "We next analyze the effect of NFKBIA amplification on the transcriptional profile of lung cancer patients." (PMID 33863364, 2021). "Strong evidence supports that the knockdown of NFKBIA confers partial resistance to erlotinib in lung cancer cell lines through elevated levels of NF-κB and that this resistance can be reversed by the inhibition of NF-κB or by the overexpression of NFKBIA." (PMID 25962919, 2015). "Interestingly, this analysis showed a profile very similar to the one previously identified in primary samples, with NFKBIA predominantly amplified in lung cancer, deleted in kidney and variously expressed in breast, large intestine and hematological tumors." (PMID 33863364, 2021).
lung carcinoma (continued). "Importantly, these results were validated in an independent cohort of TCGA lung cancer, observing an inverse correlation between β-oxidation signature and NFKBIA levels." (PMID 33863364, 2021). "In this study, we also investigated the correlations between 35 polymorphisms in 9 DNA repair genes (XRCC3, BRCA2/ZAR1L, XPC, RAD52, MAD2L2, NFKB1, NFKBIA, TNFRSF1A, and FASN) with platinum-based chemotherapy prognosis in 399 patients with lung cancer." (PMID 35899106, 2022). "In contrast, NFKBIA, PSME3, SPARCL1, CCL15, and APOA1 did not return established entries under these filters and at the time of query, indicating that, within IPA, they are not currently categorized as clinical lung cancer biomarkers." (PMID 41465234, 2025).
Sepsis (36 papers, 2011 to 2026). Sepsis is defined as life-threatening organ dysfunction caused by a dysregulated host response to infection. "Notably, NFKBIA (encoding IκBα) shows infection-dependent upregulation in SARS-CoV-2 infections, and extracellular NCOA4 exacerbates inflammatory responses through NF-κB activation in sepsis." (PMID 41557688, 2026). "In addition, NFKBIA, an inhibitor of NF-κB, is downregulated in sepsis." (PMID 40699834, 2025). "NFKBIA gene was iterated in 9 out of the 10 top pathways, MYD88 gene was enriched in 3 pathways, and IRAK4 was the only gene located on chromosome X. Their diagnostic accuracy was compared to IL6, which is used in our hospital protocol as a gold standard test for inflammatory reaction in sepsis." (PMID 34183713, 2021). "Collectively, these results pinpoint NFKBIA, NFKB2, TNFSF14, DUSP2, and PIK3C2B as key mediators of DcR3’s broad-spectrum effects in CLP-induced sepsis." (PMID 38700314, 2024). "In sepsis, RELA, CEBPB, NFKBIA, STAT6, IRF8 and SPI1 were downregulated, with no significant change in NFKB1, JUN and GLI1." (PMID 39444551, 2024).
atherosclerosis (35 papers, 2007 to 2025). A disease characterized by the build-up of fatty material and calcium deposition in the arterial wall resulting in partial or complete occlusion of the arterial lumen. "Besides this, Gene variants in NFKBIA facilitate inflammation and display a crucial role in the event of atherosclerosis and coronary artery disorders." (PMID 34335250, 2021). "IL6, CXCL8, CCL2, SOD2, NFKBIA, and BIRC3 were identified as the top 6 hub genes in the magenta module (human cardiomyocyte samples) and were mainly enriched in the NOD-like receptor signaling pathway, IL-17 signaling pathway, TNF signaling pathway, lipid and atherosclerosis signaling pathway." (PMID 36426222, 2022).
gastric cancer (35 papers, 2010 to 2025). A primary or metastatic malignant neoplasm involving the stomach. "One study reported that the expression of IκBα (encoded by NFKBIA) is increased in gastric cancer after EBV infection." (PMID 37593735, 2023). "The polymorphic variations in NFKBIA were associated with the risk of various cancers, including gastric cancer, prostate cancer and melanoma." (PMID 28384236, 2017). "On the contrary, higher levels of MT2A are associated with favorable outcome in patients with gastric cancer, and MT2A exerts anti-gastric cancer effects by complexing with MZF1 to target NFKBIA." (PMID 34663301, 2021). "In addition, circ-CEP85L hindered the malignant phenotype of gastric cancer by absorbing miR-942-5p to increase NFKBIA expression." (PMID 33292255, 2020).
colorectal cancer (34 papers, 2009 to 2025). A primary or metastatic malignant neoplasm that affects the colon or rectum. "Prior studies have identified a tumor-suppressive role of NFKBIA in Hodgkin’s lymphoma, colorectal cancer, and hepatocellular carcinoma for specific single nucleotide polymorphisms and haplotypes of NFKBIA." (PMID 38282862, 2024). "It has been shown that there is an enrichment of specific single-nucleotide polymorphisms and haplotypes of NFKBIA in Hodgkin's lymphoma, colorectal cancer and multiple myeloma, suggests that NFKBIA might be a tumor suppressor." (PMID 24504166, 2014). "In present study we have elucidated the role of 2758 A>G (rs696), in the recognition site of miR449a in the 3′ UTR of NFKB inhibitor alpha (NFKBIA) gene, in development of sporadic colorectal cancer." (PMID 29564065, 2018). "This study addresses a critical gap in understanding colorectal cancer (CRC) radiation resistance by identifying BAMBI, GADD34, NFKBIA, and NFKBID as key modulators of tumor progression and response to radiotherapy." (PMID 40332515, 2025).
glioma (33 papers, 2013 to 2025). A benign or malignant brain and spinal cord tumor that arises from glial cells (astrocytes, oligodendrocytes, ependymal cells). "While this is the first study to report this specific target protein in TNBC, NFKBIA has been implicated within the mechanism of selinexor sensitivity for other cancer contexts, such as non-Hodgkin lymphoma, MM and high-grade glioma." (PMID 39682167, 2024). "Additionally, grade III tumors presented a higher frequency of NFKBIA deletion, combined with reduced mRNA expression, suggesting an association between NFKBIA and overall glioma malignancy." (PMID 27052952, 2016). "Overall, the present findings reveal the prognostic value of NFKBIA in LGGs, reinforcing the relevance of NFκB signaling in the development and progression of gliomas." (PMID 27052952, 2016). "Accordingly, grade III gliomas expressed significantly lower levels of NFKBIA mRNA compared to grade II gliomas." (PMID 27052952, 2016). "Moreover, NFKBIA can serve as a promising prognostic marker for those with an advanced grade of gliomas." (PMID 35647198, 2022). "High GNAI, EMP3, TIMP1, ITGA5, and NMI while low PCDH7, CALCRL, and NFKBIA expressions could lead to poor prognoses in glioma patients." (PMID 35647198, 2022). "In addition, NFKBIA was found to be eliminated in about 25% of grade IV gliomas." (PMID 37775993, 2023).
COVID-19 (32 papers, 2020 to 2026). A disease caused by infection with severe acute respiratory syndrome coronavirus 2. "The myocardial injury caused by COVID-19 was associated with multiple inflammatory pathways, and IL6, NFKBIA, CSF1, CXCL1, IL1R1, SOCS3, and CASP1 were key genes of the inflammatory pathway." (PMID 37564653, 2023). "ACE2 mediated activation of ACE/AngII/AT1R axis leading to hyperactivation of NFKBIA, ultimately precipitating cytokine storm in COVID-19 patients." (PMID 33602138, 2021). "A few genes, as NFKBIA, ICAM1, CXCL8, and TNFAIP3 are involved in NF-κB signaling and TNF signaling pathways, which have been known to cause inflammation and cytokine storms, augmenting COVID-19 severity." (PMID 37701571, 2023). "Upregulated genes in early COVID-19 mortality included many involved with interferon signaling (e.g., GBP2, ISG15), the NF-κB pathway (e.g., NFKB2, NFKBIA), and TNF-α and IL-1 signaling (e.g., TANK, NOD1, RELA)." (PMID 35446789, 2022). "Genes that were found to be upregulated in the early COVID-19 mortality cases and involved with the interferon (ISG20, IRF1, GBP2) and NF-κB (NFKB2, NFKBIA, TNFAIP3) pathways showed linear decline with longer symptomatic interval." (PMID 35446789, 2022). "NF-kB signaling pathway genes (NFKBIA, NFKB1, RELA, NFKB2) were up-regulated in COVID-19 patients." (PMID 36380355, 2022). "In brief, the scRNA-seq followed by the immune transcriptomic analysis indicated an activation state (through CD69 and HLA class II genes), chemotaxis (e.g., CCL3 and CCL4), an inflammatory state (e.g., NFKBIA, PIK3R1, S100A9, etc.)in T cells, especially in CD8+T cells, in COVID-19 cases." (PMID 33717140, 2021). "Concordantly, for downstream genes of AP-1, the expression levels of some chemokine genes (e.g., CCL2, CXCL1, CXCL2, and CXCL10) were downregulated, while the expression levels of immune negative regulation genes (e.g. BCL3, NFKBIA, SOCS3, and TNFAIP3) were upregulated during the COVID-19 recovery." (PMID 33361761, 2020). "We identified upregulation of several NFκB pathway components (NFKB2 and NFKBIA) and inflammatory cytokines (CXCL9, CCL17, and CCL21) in the presence of viral transcripts, in line with the abundant literature describing these molecules in the early steps of COVID-19 pathogenesis." (PMID 37858234, 2023).
pancreatic cancer (29 papers, 2003 to 2026). "Recently, Huang and colleagues suggested that the nuclear factor κB-inhibitor α (NFKBIA), an inhibitor of the NF-κB transcription factor, which is implicated in the progression of pancreatic cancer, is a target of the miR-196a in PDAC." (PMID 27187371, 2016). "We next determined whether NFKBIA expression was negatively associated with miR-196a level in pancreatic cancer cell lines." (PMID 24504166, 2014). "In conclusion, our results suggest that miR-196a is overexpressed in pancreatic cancer cell lines, and down-regulation of miR-196a by anti-miR-196a suppresses proliferation and migration of pancreatic cancer, partially by targeting NFKBIA." (PMID 24504166, 2014). "To further determine the biological role of NFKBIA in pancreatic cancer, we investigated the effect of targeted knockdown of NFKBIA in PANC-1 cells." (PMID 24504166, 2014). "Here, we investigated the expression pattern and the biological role of miR-196a in pancreatic cancer cell lines, as well as its interaction with a metastasis-related gene, nuclear factor-kappa-B-inhibitor alpha (NFKBIA)." (PMID 24504166, 2014). "We have elucidated that NFKBIA is a target of miR196a, and miR-196a plays an important role in the development and progression of pancreatic cancer likely by targeting NFKBIA." (PMID 24504166, 2014). "They registered increased levels of miR-196a in four different pancreatic cell lines and enhanced expression of NFKBIA after miR-196a down-regulation, which promoted inhibition of migration, suggesting a direct regulation mechanism of miR-196a in migratory ability of pancreatic tumor cells." (PMID 27187371, 2016). "MiR-196a has also been shown to promote the progression of pancreatic cancer by targeting NFKBIA, which may also related to downregulation of ZG16 in pancreatic cancer." (PMID 27880730, 2016). "Furthermore, silencing NFKBIA promotes pancreatic cancer cells PANC-1 proliferation and migration, consistent with the results of ectopic miR-196a expression in the same cells." (PMID 24504166, 2014). "Taken together, our findings indicate that miR-196a is highly expressed in pancreatic cancer cell lines, and may play a crucial role in pancreatic cancer proliferation and migration, possibly through its downstream target, NFKBIA." (PMID 24504166, 2014).